HDAC7 (histone deacetylase 7)
Description:
Responsible for the deacetylation of lysine residues on the N-terminal part of the core histones (H2A, H2B, H3 and H4) (By similarity). Histone deacetylation gives a tag for epigenetic repression and plays an important role in transcriptional regulation, cell cycle progression and developmental events (By similarity). Histone deacetylases act via the formation of large multiprotein complexes (By similarity). Involved in muscle maturation by repressing transcription of myocyte enhancer factors such as MEF2A, MEF2B and MEF2C (By similarity). During muscle differentiation, it shuttles into the cytoplasm, allowing the expression of myocyte enhancer factors (By similarity). May be involved in Epstein-Barr virus (EBV) latency, possibly by repressing the viral BZLF1 gene. Positively regulates the transcriptional repressor activity of FOXP3. Serves as a corepressor of RARA, causing its deacetylation and inhibition of RARE DNA element binding. In association with RARA, plays a role in the repression of microRNA-10a and thereby in the inflammatory response. Also acetylates non-histone proteins, such as ALKBH5.
Synonyms: HD7; HD7a; HDAC7A; DKFZP586J0917
Tractability: Small molecule: an approved drug acts on it; a structure with a bound ligand is known; a high-quality ligand is known; it has a binding pocket of medium quality; it belongs to a druggable protein family. PROTAC: ubiquitination databases record sites on it; its protein half-life has been measured; a small molecule that binds it is known. Other modalities: an approved drug acts on it.
Target class: HDAC class IIa; Histone deacetylase; Epigenetic regulator; Eraser
Gene: Protein-coding gene on chromosome 12 (47,782,722 to 47,833,132, reverse strand). Ensembl gene ENSG00000061273.
Subcellular location: Nucleus; Cytoplasm
Subcellular location (Human Protein Atlas): Cytosol
Pathways (Reactome):
Disease: Constitutive Signaling by NOTCH1 HD+PEST Domain Mutants; Constitutive Signaling by NOTCH1 PEST Domain Mutants
Signal Transduction: NOTCH1 Intracellular Domain Regulates Transcription; Regulation of PTEN gene transcription
Developmental Biology: Differentiation of naive CD4+ T cells to T helper 2 cells (Th2 cells)
Gene expression (Transcription): Notch-HLH transcription pathway
Metabolism of proteins: SUMOylation of DNA damage response and repair proteins
Gene Ontology:
Molecular function: 14-3-3 protein binding; DNA-binding transcription factor binding; protein binding; protein kinase binding; protein kinase C binding; protein lysine deacetylase activity; histone deacetylase activity; histone deacetylase activity, hydrolytic mechanism; SUMO transferase activity; chromatin binding; transcription corepressor activity
Biological process: negative regulation of interleukin-2 production; negative regulation of non-canonical NF-kappaB signal transduction; negative regulation of osteoblast differentiation; positive regulation of cell migration involved in sprouting angiogenesis; protein deacetylation; regulation of mRNA processing; protein sumoylation; chromatin remodeling; negative regulation of transcription by RNA polymerase II
Cellular component: cytoplasm; cytosol; nucleus; nucleoplasm
Genetic constraint (gnomAD): Loss-of-function variants: 25 observed, 101.59 expected, observed/expected ratio (o/e) 0.25, 90% interval 0.18 to 0.34. The upper end of that interval is the gene's LOEUF score, 0.34, which puts it in group 1 of 6, group 1 being the genes least tolerant of losing a copy. Missense variants: 1,052 observed, 1,246.5 expected, observed/expected ratio (o/e) 0.84, 90% interval 0.8 to 0.89. Synonymous variants: 560 observed, 520.82 expected, observed/expected ratio (o/e) 1.08, 90% interval 1 to 1.15.
Homologues: Orthologues: macaque HDAC7 (99% identical), chimpanzee HDAC7 (94% identical), dog HDAC7 (93% identical), pig HDAC7 (91% identical), guinea pig HDAC7 (89% identical), rat Hdac7 (87% identical), mouse Hdac7 (86% identical), tropical clawed frog hdac7 (55% identical), zebrafish hdac7b (32% identical), zebrafish hdac7a (30% identical), Caenorhabditis elegans hda-5 (10% identical), Caenorhabditis elegans F43G6.17 (7% identical), and 1 more. Paralogues in human: HDAC4 (52% identical), HDAC5 (46% identical), HDAC9 (44% identical), HDAC6 (26% identical), HDAC10 (12% identical), HDAC1 (11% identical), HDAC2 (10% identical), HDAC3 (10% identical), HDAC8 (10% identical), HDAC11 (9% identical).
Diseases named in the same sentence as HDAC7 in open-access papers:
HDAC7 is named in the same sentence as 135 diseases in open-access papers, as found by Europe PMC text mining. Sharing a sentence is not in itself a finding about the gene and the disease. The quoted sentences say what the papers report.
breast carcinoma (21 papers, 2015 to 2025). "HDAC2 is associated with poor survival and relapse of cancer, HDAC3 promotes oncogenesis and is a good target for therapeutics, HDAC5 is known to increase the stemness of breast cancer cells, and HDAC7 protein is associated with reoccurrence of breast cancer." (PMID 40426890, 2025). "Consistent with this, the mRNA expression heat-map illustrates the remarkable association of these genes with HDAC7 mRNA expression levels in human breast cancer." (PMID 36038558, 2022). "High level of HDAC7 is frequently associated with advanced cancers and contributes to the poor prognosis of lung and breast cancer patients." (PMID 36163081, 2022). "The invalidation of HDAC2 and HDAC7 has been reported to be associated with proliferation arrest respectively in MCF-7 breast cancer cell line and in mucoepidermoid carcinoma cells, but not yet investigated on the potential induction of the senescent phenotype in normal cells." (PMID 34253688, 2021). "In breast cancer model, HDAC7 inhibition with TMP195 induces recruitment and differentiation of phagocytic and stimulatory macrophages, resulting in enhanced antitumor efficiency." (PMID 39806423, 2025). "Caslini reported that HDAC7 promotes the growth and metastasis of breast cancer by downregulating the acetylation of H3K27." (PMID 39736396, 2025). "HDAC7 is thought to promote breast cancer cell survival through its capacity, in cooperation with HDAC1, to deacetylate HSP70, which limited autophagic cell death of CSCs." (PMID 35303381, 2023). "Studies have also reported that HDAC7 is crucial in cancer metastasis, for instance, in breast cancer, nasopharyngeal cancer, and ovarian cancer." (PMID 36653340, 2023). "Several previous studies have demonstrated that HDAC7 has a carcinogenic role in breast cancer, ovarian cancer, and glioma." (PMID 35277183, 2022). "Abnormal HDAC7 expression has been observed in lung cancer, stomach cancer, breast cancer, ovarian cancer, glioma, and hematological lymphoma." (PMID 35595735, 2022). "Remarkably, almost half of the ET-125 genes in BPLER cells (56/125) demonstrate statistically significant correlation with HDAC7 expression in clinical breast cancer samples." (PMID 36038558, 2022). "All the breast cancer cell lines we tested indicate that ZNF92 protein is co-expressed with HDAC7 in the nucleus." (PMID 36038558, 2022). "Previously, we reported that HDAC1 and HDAC7 individually upregulate 1512 and 812 genes respectively in breast cancer cells." (PMID 36038558, 2022). "In this work, we proposed the ibotenic acid as lead compound for the development of novel HDAC7 inhibitors, due to its antiproliferative activity in human breast cancer cells (MCF-7)." (PMID 33255661, 2020). "The in vitro assays were performed on MCF-breast cancer cells, a cellular line with overexpression of HDAC7." (PMID 33255661, 2020). "Since a recent study claimed a role of HDAC7 in breast cancer stem cells, we compared sphere generation by HDAC7−/− and HDAC7+/+ cells." (PMID 31081251, 2019). "When luminal A breast cancer patients were stratified according to the expression levels of the HDAC7‐secretome signature, patients with high levels of the signature showed a better prognosis." (PMID 31081251, 2019). "Direct repression or inactivation of HDAC7 through HDAC1 and HDAC3 inhibition downregulates multiple super‐enhancers (SEs) and SE‐associated oncogenes, suppressing cancer stem cell phenotypes in breast cancer." (PMID 38827027, 2024). "Collectively, these studies reveal multifaceted roles for HDAC7 in breast cancer." (PMID 35303381, 2023). "HDAC7 is positively correlated with breast cancer recurrence, it promotes the transformation of epithelial cells, it appears to contribute to the proliferation and maintenance of CSC stemness, and it may limit anti‐tumour responses of immune cells." (PMID 35303381, 2023). "HDAC7 mRNA was elevated in breast cancer tissues by comparison with normal breast tissue." (PMID 35303381, 2023).
breast carcinoma (continued). "Besides, HDAC7 inactivation results in the inhibition of breast cancer stem cell phenotype by downregulating c-Myc." (PMID 36653340, 2023). "Other evidence also suggests that HDAC7 may contribute to breast cancer progression through immune modulation." (PMID 35303381, 2023). "Abnormal expression of HDAC7 has also been demonstrated in breast cancer." (PMID 35303381, 2023). "Moreover, experimental studies have proven that HDAC7 overexpression could promote the growth of lung cancer, breast cancer, glioma, and nasopharyngeal carcinomas cells." (PMID 36163081, 2022). "We were able to validate multiple correlations with DEK expression and both down- and up-regulated genes in primary human breast cancers, including CCL5, CDC45, CDH1, and HDAC7." (PMID 32708944, 2020). "In breast cancers, miR-34a suppresses HDAC1 and HDAC7 expression and its level is inversely correlated with HDAC1 and HDAC7 activity, as well as tumor characteristics such as grade and stage." (PMID 28933369, 2017). "In addition, it has been shown that miR-34a regulates cell survival and therapy resistance in breast cancer by targeting HDAC1 and HDAC7 in breast cancer." (PMID 37835417, 2023). "Another study compared serum samples from patients with recurring versus nonrecurring breast cancer, finding that protein levels of HDAC7 were significantly higher in patients with recurring disease." (PMID 35303381, 2023). "This HDAC7‐regulated secretome signature predicts negative prognosis for luminal A breast cancers." (PMID 31081251, 2019).
glioma (21 papers, 2015 to 2026). A benign or malignant brain and spinal cord tumor that arises from glial cells (astrocytes, oligodendrocytes, ependymal cells). "Several studies have shown that HDAC7 is dysregulated in many cancers, including nasopharyngeal carcinoma, gastric cancer, and glioma; this dysregulation is associated with metastasis and a poor prognosis and is the main target of several HDAC inhibitors (HDACis)." (PMID 35595735, 2022). "It has been reported that HDAC7 can deacetylate β-catenin to affect its phosphorylation and lead to its ubiquitination degradation in glioma." (PMID 39736396, 2025). "Elevated expression of HDAC7 has been observed in various malignant tumors, glioma, colorectal, and gastric cancers." (PMID 40465706, 2025). "Dysregulated HDAC7 expression has been validated in various cancers, such as ovarian cancer, and glioma." (PMID 36653340, 2023). "A previous study reported that abnormal HDAC7 expression levels are correlated with cell proliferation, metastasis, and angiogenesis in different cancers, such as colorectal cancer, glioma, and gastric cancer." (PMID 36653340, 2023). "Aberrant expression of HDAC7 has been observed in gastric, breast, and ovarian cancer, along with glioma and hematological malignancies, where high expression of HDAC7 has been correlated with metastasis and poor prognosis." (PMID 35277183, 2022). "ZNF326 has been reported to bind to specific promoter regions through its transcriptional activation domain and zinc finger structure in glioma cells to activate HDAC7 transcription." (PMID 36227941, 2022). "Previous studies have showed that HDAC7 was involved in the malignant phenotype of glioma regulated by ZNF326." (PMID 32284070, 2020). "The proliferation and invasiveness of glioma cells were reversed by HDAC7 silencing or HDAC7 inhibition, as confirmed by MTT assay and Transwell assay, respectively." (PMID 30691485, 2019). "Consistently, compared with the ZNF326 IHC staining results, the expression of HDAC7 was positively correlated with the expression of ZNF326 in gliomas." (PMID 30691485, 2019). "HDAC6 expression was significantly increased in all gradesof gliomas, whereas HDAC7 and HDAC10 were significantly increasedonly in ODIII and GL tumors." (PMID 25791281, 2015). "Additionally, the HDAC7-high group exhibited a higher proportion of patients with recurrent glioma than the HDAC7-low group in CGGA dataset." (PMID 39629136, 2024). "Both RNA and protein levels of HDAC7 were significantly increased with higher glioma grade." (PMID 39629136, 2024). "In addition, ZNF326 is not only highly expressed in glioma, but also positively correlated with HDAC7 expression, thus confirming the role of HDAC7 oncogene." (PMID 36227941, 2022). "It was reported that ZNF326 could activate HDAC7 transcription by binding to a specific promoter region via its transcriptional activation domain and zinc-finger structures in glioma cells." (PMID 35545840, 2022). "Furthermore, ZNF326 was not only highly expressed in glioma but was also positively correlated with the expression of HDAC7, which identified the oncogenic role of HDAC7." (PMID 35545840, 2022). "Interestingly, a recent finding in glioma indicated that decreased acetylation levels of β-catenin induced by HDAC7 changed steric hindrance of β-catenin, thus inhibiting its phosphorylation level and activation of the Wnt pathway." (PMID 35277183, 2022). "Univariate Cox regression indicated that high expression levels of HDAC1, HDAC3, HDAC7 and HDAC9 were associated with poor OS of glioma, and elevated expression levels of HDAC4, HDAC5, HDAC6 and HDAC11 were associated with a favorable prognosis of glioma." (PMID 35545840, 2022).
glioma (continued). "Interestingly, we found that the expression of HDAC7 in NHA cell lines was also significantly lower than that in other glioma cell lines, similar to ZNF326 expression." (PMID 30691485, 2019). "Furthermore, HDAC7 expression was higher in MES subtype glioma and GSCs." (PMID 39629136, 2024). "We first performed the univariate cox regression and found that the elevated expressions of HDAC7, HDAC3, and HDAC1 were associated with poor prognosis while increased expressions of HDAC6, HDAC5, HDAC4, and HDAC11 were favorable for prognosis in low-grade glioma." (PMID 36227941, 2022). "Our results align with a previously demonstrated better outcome for high-expressing patients of specific class IIA HDAC members, specifically in non-small cell lung carcinomas, HDAC7 in triple-negative breast cancers, and HDAC4/5 in gliomas." (PMID 39063083, 2024). "Then, using six HDAC genes (HDAC1, HDAC3, HDAC4, HDAC5, HDAC7, and HDAC9), we established a prognostic model for glioma patients, and this prognostic model was validated in an independent cohort population." (PMID 35545840, 2022). "A model based on six HDAC genes (HDAC1, HDAC3, HDAC4, HDAC5, HDAC7, and HDAC9) can predict the overall survival of glioma patients well and these genes are potential therapeutic targets." (PMID 35545840, 2022). "Then, using six HDAC genes (HDAC1, HDAC3, HDAC4, HDAC5, HDAC7, and HDAC9), we established a prognostic model for glioma patients, and this prognostic model was validated in an independent cohort." (PMID 35545840, 2022). "Specifically, the mRNA level of HDAC1 (p = 1.25e−13), HDAC3 (p = 2.51e−09), HDAC7 (p = 1.43e−19), and HDAC8 (p = 3.48e−10) showed an increasing trend with glioma grade progressing." (PMID 34540896, 2021). "The DFS-oriented study using GEPIA data showed that more transcripts of HDAC1 (HR:3.0, p < 0.0001), HDAC3 (HR:2.7, p = 2.1e−15), HDAC7 (HR:2.1, p = 3e−09), and HDAC9 (HR:1.5, p = 0.0026) accompanied with less DFS probabilities in glioma patients." (PMID 34540896, 2021). "Our findings reveal OLIG2+ glioma stem-like cells as critical mediators of immune evasion and identify the OLIG2/HDAC7/CXCL10 axis as a potential therapeutic target to enhance immune checkpoint inhibitor efficacy and improve immunotherapy outcomes in aggressive GBMs." (PMID 41591814, 2026). "Ten glioma samples (5 IDH1 wildtype and 5 IDH1 mutant) were stained for various HDAC genes using internally validated antibodies (HDAC1, HDAC2, HDAC3, HDAC4, HDAC5, HDAC6 and HDAC7) and scored by a blinded neuropathologist (AK)." (PMID 37528157, 2023). "High HDAC7 mRNA expression was significantly correlated with OS and DFS in patients with glioma." (PMID 35359455, 2022). "The OS analysis based on GEPIA revealed that the glioma patients with high expression levels of HDAC1 (HR:3.9, p < 0.0001), HDAC2 (HR:1.3, p = 0.024), HDAC3 (HR:4.4, p < 0.0001), and HDAC7 (HR:3.3, p < 0.0001) would face with more risks compared to the ones with low expression of these genes." (PMID 34540896, 2021). "Therefore, which gene, such as HDAC7, ERCC1, LTBP4 and ZNF383, could play a major role in glioma proliferation need further study and investigation." (PMID 30691485, 2019). "qPCR was adopted to detect the expression of HDAC1, HDAC3, HDAC4, HDAC5, HDAC7 and HDCA9 in nontumor and glioma tissues." (PMID 35545840, 2022). "The expression levels of HDAC1, HDAC3, HDAC7, and HDAC9 were significantly elevated in the glioma patients compared with the nontumor group." (PMID 35545840, 2022). "IHC staining of ZNF326 and HDAC7 expressions in gliomas with different grades outlined below: (B, C): ZNF326 and HDAC7 were both negative expressed in pilocytic astrocytoma (grade I, Magnification 400×)." (PMID 30691485, 2019).